HIF1A (hypoxia inducible factor 1 subunit alpha)
Diseases named in the same sentence as HIF1A in open-access papers (continued):
Sharing a sentence is not in itself a finding about the gene and the disease.
pneumonia (19 papers, 2012 to 2026). An acute, acute and chronic, or chronic inflammation focally or diffusely affecting the lung parenchyma, caused by an infection in one or both of the lungs (by bacteria, viruses, fungi, or mycoplasma.). "This shows that pneumonia aggravation by a high-calorie diet is associated with interference in the HIF-1α-mediated HPA axis." (PMID 40724811, 2025). "In these patients, HIF1α activation has been proposed to initiate a cytokine storm, which can cause severe implications, such as pneumonia and ARDS, that eventually result in organ failure, or even death." (PMID 36324747, 2022). "Our results indicate that siderophores act directly on the host to induce inflammatory cytokines and bacterial dissemination and that HIF-1α is a susceptibility factor for bacterial invasion during pneumonia." (PMID 27624128, 2016). "This suggests that the aggravation of pneumonia caused by a high-calorie diet may be associated with hypothalamus HIF-1α-mediated HPA axis disorder." (PMID 40724811, 2025). "Hypothalamus proteomics and Western blot results proved that a high-calorie diet upregulated the expression level of hypothalamus hypoxia-inducible factor-1 alpha (HIF-1α) in juvenile rats with pneumonia, and this mechanism is associated with reduced HIF-1α ubiquitination." (PMID 40724811, 2025). "To further validate whether HPA axis changes caused by a high-calorie diet in juvenile rats with LPS-induced pneumonia were associated with the hypothalamus HIF-1α signaling pathway, we used an HIF-1α inhibitor to treat rats in the GP + 2ME-2 group." (PMID 40724811, 2025). "In addition, recent studies have shown that hypoxia-inducible factor 1-alpha (HIF-1α) is associated with the production of proinflammatory molecules in the severe pneumonia caused by H1N1 infection." (PMID 34803696, 2021). "Therefore, studies have shown that a high-calorie diet can upregulate the HIF-1α expression level in the hypothalamus of rats with LPS-induced pneumonia, and its mechanism may be associated with decreased HIF-1α ubiquitination." (PMID 40724811, 2025). "This intervention also suppressed HIF-1a activity and lung tissue glycolysis metabolism, decreased the number of M1-type macrophages, and increased the number of M2-type macrophages, effectively alleviating lung damage caused by influenza virus-induced pneumonia." (PMID 39161892, 2024). "Our further validation found that LPS nebulization alone can increase the protein expression level of HIF-1α in the hypothalamus, while a high-calorie diet further increases that level in the hypothalamus of rats with pneumonia." (PMID 40724811, 2025). "This somewhat suggests that the aggravation of LPS-induced pneumonia by a high-calorie diet is related to interference with the hypothalamus HIF-1α signaling pathway." (PMID 40724811, 2025). "A high-calorie diet boosts HIF-1α signaling in the hypothalamus and exacerbates LPS-induced pneumonia by disrupting the HPA axis." (PMID 40724811, 2025). "We observed that a high-calorie diet increased the HIF-1α expression level in the hypothalamus in rats with LPS-induced pneumonia and resulted in HPA axis imbalance." (PMID 40724811, 2025). "This indicates that the inhibition of HIF-1α expression in the hypothalamus can somewhat reverse the aggravation of pneumonia via a high-calorie diet." (PMID 40724811, 2025). "In a similar mouse pneumonia model, hypoxia-induced stabilization of HIF-1α increased morbidity and mortality during intratracheal S. pneumoniae infection." (PMID 38283697, 2024). "During pneumonia, K. pneumoniae siderophores elicit robust lung inflammation and stabilization of alveolar HIF-1α that results in dissemination to secondary sites." (PMID 37463183, 2023). "This proof-of-principle study sought to enhance the therapeutic potential of MSCs in experimental lung injury due to pneumonia by stabilizing the transcription factor HIF-1α with the pharmacological agent AKB-4924." (PMID 29780805, 2018).
pneumonia (continued). "Therefore, mitochondrial ROS-mediated stabilization of HIF-1α likely contributes to exaggerated neutrophilic responses and links mitochondrial metabolism with neutrophilic lung inflammation in the context of pneumonia." (PMID 38283697, 2024). "Moreover, Pseudomonas aeruginosa entry into alveolar cells was decreased under hypoxia and after DMOG treatment, confirming the role of HIF-1α in an in vivo pneumonia model." (PMID 26731748, 2016). "What’s more, alveolar and lung interstitial macrophages from myeloid-specific HIF-1α-deficient mice produced a lower level of immunity, suggesting the importance of HIF-1α expressed in lung macrophages in protective innate immunity during pneumonia caused by K. pneumoniae." (PMID 36506034, 2022). "Consequently, we hypothesized that HIF-1α stabilization in MSCs would enhance their therapeutic efficacy in experimental lung injury and pneumonia, potentially by improving cell survival in the face of inflammatory, cytotoxic stimuli." (PMID 29780805, 2018). "In the present study, we observed an upregulation of HIF-1a expression in the lung tissue of mice with influenza virus-induced pneumonia, and MXSG administration reduced HIF-1a expression." (PMID 39161892, 2024). "Since both mouse strains had pneumonia and we did not measure oxygen saturations, we cannot exclude an influence of a hypoxia-induced increase in HIF-1α in the lungs of both strains after infection." (PMID 23006927, 2012).
papillary thyroid cancer (18 papers, 2016 to 2025). "Significantly, loss of NOX4 in human papillary thyroid cancer cells decreases HIF1α targeting genes such as SLC2A1 and CA9, highlighting the potential importance of NOX4-mediated metabolic reprogramming in thyroid tumor." (PMID 30367082, 2018). "The SIRT6/HIF-1α axis could be a new therapeutic target and diagnostic marker of papillary thyroid cancer." (PMID 30675128, 2019). "Sirt6/Hif-1α axis promotes papillary thyroid cancer progression by inducing epithelial-mesenchymal transition (EMT)." (PMID 32711549, 2020). "Moreover, the HIF-1α/YAP signaling axis modulates glucose/iodine metabolism in papillary thyroid cancer progression." (PMID 37684641, 2023). "Thus, the aim of this study was to investigate the expression of HIF-1α/PKM2 axis in papillary thyroid carcinoma and its roles in the development of PTC." (PMID 36897686, 2023). "This study examined whether SIRT6 promotes epithelial–mesenchymal transition (EMT) of papillary thyroid cancer through hypoxia inducible factor-1α (HIF-1α)." (PMID 30675128, 2019). "This study identified HIF-1a/PKM2 axis as potential molecular marker for predicting the invasion and progression of papillary thyroid carcinoma." (PMID 36897686, 2023). "Expressions of HIF-1α and PKM2 in normal thyroid follicular epithelium and papillary thyroid carcinoma." (PMID 36897686, 2023). "This study aimed to investigate the expression of HIF-1α and PKM2 in papillary thyroid carcinoma (PTC) and its correlation with the patients clinicopathological features and with tumor invasion and metastasis." (PMID 36897686, 2023). "Our results support this observation by showing that, as in papillary thyroid carcinoma (PTC), NOX4, HIF-1α, GLUT-1, and VEGF-A are increased in Th1 cytokines-treated human thyroid cells and in Hashimoto’s thyroid samples." (PMID 33916948, 2021). "Similar result was also acquired in VSMC and papillary thyroid cancer cell lines TPC-1 and B-CPAP26, which indicated a universal promotion of SIRT6 at HIF-1α." (PMID 33436551, 2021). "In papillary thyroid carcinoma (PTC) tissues, high expression of LSD1 stabilizes HIF-1α to avoid its proteasomal degradation, and database prediction shows that HIF-1α is enriched near the miR-146a promoter region." (PMID 33109235, 2020). "mRNA levels of HIF-1α and HIF-2α were analyzed by real-time PCR in a sample set containing non-neoplastic lesions (nodular goiters, NG), follicular adenomas (FA), papillary carcinomas (PC) and follicular carcinomas (FC)." (PMID 29084538, 2017). "The aim of this study was to detect the expression of hypoxia-inducible factor (HIF)-1α and HIF-2α in papillary thyroid carcinoma (PTC) compared with normal thyroid tissues." (PMID 26846782, 2016). "However, research about the relationship between HIF-1α/PKM2 axis and the progression of papillary thyroid carcinoma is still scare." (PMID 36897686, 2023). "In conclusion, these data demonstrated that different expression and clinicopathologic significance of the HIF-1α/PKM2 feedback loop did exist between PTC and normal thyroid tissues, supporting the linkage between HIF-1α/PKM2 feedback loop and the progression of papillary thyroid carcinoma." (PMID 36897686, 2023). "Thus, the aim of this study was to investigate the expression of HIF-1α and HIF-2α in papillary thyroid carcinoma and its roles in the development of PTC." (PMID 26846782, 2016).
varicocele (18 papers, 2010 to 2024). A condition characterized by the dilated tortuous veins of the spermatic cord with a marked left-sided predominance. "HIF1α was upregulated in a rat varicocele model, a hypoxic condition associated with increased apoptosis." (PMID 39631561, 2024). "Previous studies have reported that patients with asthenozoospermia or varicocele exhibited significantly lower sperm motility and elevated HIF-1α levels." (PMID 38605082, 2024). "Multiple studies have demonstrated that hypoxia-inducible factor 1-alpha (HIF-1α), a well-known marker of hypoxia, is upregulated in males with varicoceles." (PMID 38392299, 2024). "HIF-1α reduction in varicocele rats improves seminiferous tubules, spermatogenic cell density/arrangement, reduces apoptosis, and downregulates VEGF/PI3K/Akt pathway." (PMID 39409717, 2024). "Previous studies demonstrated that a high expression of HIF-1α triggers the apoptosis pathway in asthenozoospermic patients with varicocele." (PMID 37686330, 2023). "When operated testes of varicocele plus Se treated rats were considered, the seminiferous tubules showed HIF-1α positive cells, and the expression of Leydig cells was lower if matched to varicocele rats." (PMID 37686330, 2023). "In both operated and CL testes of varicocele rats challenged with lycopene and Se, HIF-1α positivity of elongated spermatids, spermatozoa, and Leydig cells was comparable to sham." (PMID 37686330, 2023). "After silencing the HIF1A gene in the testis of varicocele rats, the apoptosis of spermatogenic cells was reduced and the spermatogenic function of the testes was significantly improved." (PMID 35464385, 2022). "Studies have shown that hypoxia can increase the expression of HIF-1α in the testis of rats with varicocele, and the apoptosis of spermatogenic cells is significantly increased." (PMID 35401656, 2022). "The results of PCR analysis showed that induced varicocele upregulated the expression level of the HIF1‐α in the varicocele and lycopene subgroups compared to the control group (p < .05)." (PMID 35592276, 2022). "Our finding also indicated that the expressions of HIF1‐α and Bax mRNA were higher and Bcl2 was lower in the testis tissues of the rats with varicocele than healthy rats (p < .05)." (PMID 35592276, 2022). "A growing body of research has shown the overexpression of HIF1‐α in patients with varicocele and varicocele animal models." (PMID 35592276, 2022). "The western blot (WB) result of HIF-1α proved that varicocele made a hypoxic environment, while lycopene ameliorated oxidative stress." (PMID 34055003, 2021). "Another study revealed that silencing HIF-1α significantly downregulated the expression of Bax and cleaved caspase-3 in the testes of varicocele rats." (PMID 34589489, 2021). "In humans, the expression of HIF-1α protein was 7 times higher in patients with varicocele (testicular hypoxia) than in normal volunteers." (PMID 34589489, 2021). "In varicocele, hypoxia leads to an elevation in HIF-1α expression and subsequently vascular endothelial growth factor (VEGF), which ultimately regulates cellular response to hypoxia." (PMID 32353040, 2020). "For example, in the mouse testis, HIF-1α regulates the expression of the 3β-hydroxysteroid dehydrogenase type I (Hsd3b1) gene in Leydig cells, and up-regulated expression of HIF-1α has been reported in experimentally-induced varicoceles in the rat testis." (PMID 23216940, 2012). "Increased expression of HIF1A, an hypoxia-inducible transcription factor, is present in the internal spermatic vein of patients with varicocele." (PMID 20576090, 2010). "In varicocele testes, there was an increased expression of HIF-1α in Leydig cells, which could be related to the hypoxic conditions of the interstitial tissues in both experimental procedures." (PMID 37686330, 2023).
varicocele (continued). "Studies have shown that when the CRISPR/Cas9 gene editing technique is applied to silence the HIF-1α gene of varicocele rat testis, HIF-1α regulates the spermatogenesis in fertilized varicocele rats and the PI3K/Akt signaling pathway plays a regulatory role in this process." (PMID 35401656, 2022). "Also, there was a significant increase in Bax, HSPA2, and HIF1‐α expressions in the varicocele group compared to the control group." (PMID 35592276, 2022). "Also, they showed silencing the HIF1‐α gene decreased apoptosis in germ cells and improved the function of spermatogenesis in the varicocele rats." (PMID 35592276, 2022). "In rat models, silencing the HIF-1α gene in varicocele testes using the CRISPR/Cas9 gene editing technique significantly reduced the rate of apoptosis of spermatogenic cells and improved spermatogenic function by downregulating the VEGF/PI3K/AKT signaling pathway." (PMID 34589489, 2021). "As to the reduction in testosterone levels observed in the varicocele group, this could be related to the increase in HIF-1α in Leydig cells, indicating a hypoxic suffering of these cells, which is able to interfere with steroid synthesis in the interstitial cells." (PMID 37686330, 2023). "Our data suggest that HIF-1α could play important roles in late testis I/R and that this transcriptional factor could be modulated by PDRN and Se association, which, together with surgery, could be considered a tool to improve varicocele-induced damages." (PMID 36361932, 2022). "On the contrary, no positivity for HIF-1α was observed in the greatly damaged seminiferous tubules of both operated and CL testes of varicocele rats, while a higher expression was present in Leydig cells when compared to sham rats." (PMID 37686330, 2023). "Interestingly, the suppression of elevated testicular HIF1α expression to normal levels improved the negative effects in the rat varicocele model." (PMID 39631561, 2024). "Apoptosis of spermatogenic cells was observed in the varicocele rat model when the expression of p70S6K and P-P70S6K in the nucleus and cytoplasm of spermatogenic cells was significantly increased and the expression of p-Akt and p-p70S6K decreased after HIF-1α gene silencing." (PMID 35401656, 2022).
chronic lymphocytic leukemia (17 papers, 2015 to 2025). "Overexpressed HIF1A mRNA in peripheral blood mononuclear cells is related to poor overall survival of chronic lymphocytic leukemia." (PMID 36249421, 2022). "In this study, we addressed the potential role of AHR and HIF-1α in chronic lymphocytic leukemia (CLL) development in vivo." (PMID 34572746, 2021). "Formation of a triple HSP90/HIF-1α/BCL-2 (B-cell CLL/lymphoma 2) complex results in stabilization of HIF-1α (hypoxia-inducible factor 1) under hypoxic conditions." (PMID 31659567, 2020). "In patients with chronic lymphatic leukemia HIF-1α correlates with CXCR4 expression and appears to have a relevant role in pathogenesis." (PMID 29865880, 2018). "In addition, experiments have confirmed that EZN-2208 can show significant anti-early leukemic activity in chronic lymphocytic leukemia (CLL) by acting as an HIF-1α inhibitor." (PMID 36139386, 2022). "CDK7 may promote HIF1α transcriptional activity in chronic lymphocytic leukemia cell lines, and the expression of GLUT1, GLUT3, Hexokinase 1, and Hexokinase 2 is regulated by HIF1α43,44." (PMID 31784510, 2019). "Furthermore, some of these drugs e.g., Emetine and Cephaline were recently shown to be highly active against primary chronic lymphocytic leukemia cells by repressing HIF-1α and disturbing intracellular redox homeostasis." (PMID 31861091, 2019). "In chronic lymphocytic leukemia (CLL), HIF-1α serves as a pivotal oncogene that drives CLL cell survival and proliferation through multiple molecular mechanisms." (PMID 40791591, 2025). "In chronic lymphocytic leukemia, microvesicles activate the AKT pathway and elevate the production of hypoxia-induced factor 1-alpha (HIF-1α) and vascular endothelial growth factor (VEGF), changing the bone marrow niche in a malignant direction." (PMID 37047428, 2023). "In chronic lymphocytic leukemia (CLL) cells, HIF-1α is constitutively expressed compared to normal B cells, and it acts as an important regulator of the interplay between the neoplastic clone and the tumor microenvironment." (PMID 34207596, 2021). "Doxorubicin mediates resistance in chronic lymphocytic leukemia (CLL) by upregulating RhoA/RhoA kinase, Ras/ERK1-2, Akt, HIF-1α, and P-gp activities; simvastatin inhibits this effect, overcoming doxorubicin resistance." (PMID 34065757, 2021). "In chronic lymphocytic leukemia (CLL), HIF-1α promotes bone marrow neovascularization, regulates the expression of chemokine receptors and cell adhesion molecules (such as CXCR 4, CXCL 12, etc.), thereby maintaining CLL cells survival within the bone marrow microenvironment." (PMID 35684364, 2022).